Y_RNA (Y RNA )
Gene: Miscellaneous RNA gene on chromosome 4 (112,755,816 to 112,755,917, reverse strand). Ensembl gene ENSG00000202536.
Homologues: Orthologues: chimpanzee Y_RNA (97% identical), macaque Y_RNA (89% identical). Paralogues in human: Y_RNA (87% identical), RNY3 (86% identical), Y_RNA (86% identical), Y_RNA (85% identical), RNY3P1 (84% identical), Y_RNA (84% identical), Y_RNA (83% identical), RNY3P16 (82% identical), Y_RNA (82% identical), RNY3P2 (81% identical), Y_RNA (81% identical), RNY3P13 (80% identical), and 95 more.